IL6 (interleukin 6)
Diseases named in the same sentence as IL6 in open-access papers (continued):
Sharing a sentence is not in itself a finding about the gene and the disease.
periodontitis (continued). "In our study, we demonstrated that ligature-induced periodontitis can upregulate the levels of inflammatory factors, especially IL-6 and IL-21." (PMID 33757547, 2021). "Tissue destruction in periodontitis is driven by an expansion of TH17 cells in an interleukin (IL)-6 and IL-23 dependent manner, due to changes in microbial community structure." (PMID 34950607, 2021). "Pro-inflammatory cytokines such as IL-1β, TNF-α and IL-6 are produced by monocytes, and macrophages and play a critical role in the pathogenesis of periodontitis." (PMID 34481488, 2021). "Previous studies have shown that circulating IL-6 levels are obviously increased in patients with periodontitis." (PMID 33757547, 2021). "The levels of salivary IL-6 appear to be increased in patients affected by Chronic Periodontitis as compared to healthy controls." (PMID 33916672, 2021). "Rats with periodontitis (group 3) expressed significantly higher immunoreactivities of IL-6 and TNF-α and lower IL-10 immunoreactivity compared to those other groups (p<0.05)." (PMID 34586188, 2021). "In patients with periodontitis, inflammatory markers (IL-6, IL-10, TNF-α, C-reactive protein, and ALP) in the gingival crevicular fluid are increased and directly correlated with the severity of the disease." (PMID 33430249, 2021). "IL-6, a pro-inflammatory cytokine with pleiotropic biological activities, plays a key role in RA and periodontitis." (PMID 33716675, 2021). "In periodontitis, there is a local increase in the concentration of inflammatory mediators (IL-1, IL-6, and TNF-α), which not only have a destructive effect on the periodontium but can also initiate the formation of atherosclerotic plaque." (PMID 33477706, 2021). "A multicentre Stability Study showed a link between inflammation markers like hsCRP and interleukin-6 and periodontitis." (PMID 33407375, 2021). "Interleukin-6 572C/G and RS1800796 polymorphisms appear as genetic risk factors for periodontitis patients in the Asian population." (PMID 33916672, 2021). "The saliva of the studied patients with periodontitis yielded higher levels of IL-6 than that of health controls." (PMID 35048045, 2021). "IL-1β plays an important role in the pathogenesis of periodontitis also by regulation of the IL-6 production in a variety of cell types, including fibroblasts and epithelial cells." (PMID 33467650, 2021). "TNF-α, IL-1β, and IL-6 are the most important inflammation markers of periodontal disease, and its increase has been very well explained in periodontitis as a response to infection with the periodontal pathogens (Porphyromonas gingivalis, etc.)." (PMID 33746772, 2021). "In particular, ginsenosides inhibited the release of the pro-inflammatory cytokines, TNF-α and IL-6, which are important inflammatory factors in periodontitis." (PMID 33917440, 2021). "During the inflammation generated by periodontitis, there is a significant increase in interleukin expression (IL-1β, IL-6) and transforming growth factor-1β (TGF-1β), which play a key role." (PMID 34833990, 2021). "In patients with periodontitis, LI-6 and IL-8 are abnormally elevated, and IL-6 in the cerebrospinal fluid after subarachnoid hemorrhage can predict infection." (PMID 34925324, 2021). "Compared with the periodontitis group, the levels of IL-17A, IL-10 were downregulated and IL-6,TGF-β1 were upregulated in the SPRC groups." (PMID 35087796, 2021). "In periodontitis, IL‐1, IL‐6, IL‐17A, and tumor necrosis factor‐α (TNF‐α) known as pro‐inflammatory cytokines cause body immune responses to oral bacteria specifically called Porphyromonas gingivalis." (PMID 34272761, 2021). "The inflammatory response associated with cardiovascular disease and also chronic periodontitis is modulated by proinflammatory cytokines such as TNF-α, IL-1, and IL-6." (PMID 34884653, 2021).
periodontitis (continued). "Further blood analysis revealed that the experimental periodontitis mice had elevated LPS levels (P <0.05), while changes in inflammatory factors IL-6 and TNF-α were consistent with LPS." (PMID 35118014, 2021). "In this regard, the authors of this article have analysed the literature data concerning IL-6 and IL-17, which is also overexpressed in periodontitis." (PMID 33975613, 2021). "IL-6 concentrations of 1285.7 pg/ml and 1332.2 pg/ml were detected, respectively, following exposure to saliva (50% dilution) from the periodontitis and healthy subjects." (PMID 35048079, 2021). "We have earlier shown that these patients with periodontitis had higher salivary levels of interleukin 6 (IL-6) and IL-1β, and elevated pro-inflammatory: anti-inflammatory ratio compared to H." (PMID 35048045, 2021). "In obese rats, adipose tissue inflammation was significantly aggravated by periodontitis with an increased expression of pro-inflammatory cytokines such as Interleukin-6 (IL-6) and Tumor Necrosis Factor α (TNF-α)." (PMID 33919425, 2021). "In periodontitis, proinflammatory cytokines, such as IL-1β, IL-6, IL-8, and TNF-α, seem to be the major mediators, involved in the destruction of periodontal tissue." (PMID 34035660, 2021). "As mentioned, not only IL-6 levels but also CCL27 and CXCL13 high levels were previously associated with periodontitis." (PMID 35048045, 2021). "Periodontitis is also associated with elevated levels of CRP and IL-6 with varying levels of IL-6 accompanied with disease progression." (PMID 34452136, 2021). "Periodontitis is a chronic inflammatory disease that is characterized by elevated production of several pro-inflammatory cytokines, including IL-1β, IL-6, and TNFα, in the oral cavity, which can further contribute to low-grade systemic inflammation." (PMID 33562334, 2021). "Patients with Periodontitis and Peri-implantitis present higher levels of inflammatory markers such as IL-6, TGF-1β, IL-1β, and IL-8 compared to healthy patients." (PMID 34412595, 2021). "Conversely, elevated blood levels of CRP or IL-6 are commonly observed in periodontitis, indicating systemic reactions to the local infection and inflammation within the oral cavity." (PMID 32827080, 2021). "Neutrophils in periodontitis also have a higher cytokine reactivity as the expression of chemokines and the release of cytokines (IL-1β, IL-6, IL-8, and TNF-α) are higher in neutrophils isolated from late-onset periodontitis patients." (PMID 33777839, 2021). "Increase of such proinflammatory cytokines as: IL-1α, IL-1β, TNF-α, IL-6, and IL-17 were shown in patients with acute or chronic periodontitis." (PMID 33467650, 2021). "IL-1β, IL-6, and TNF-α are the main inflammatory cytokines of periodontitis, which contribute to inflammation and bone loss during periodontitis." (PMID 34592963, 2021). "Three studies only assessed the serum IgG levels of the oral bacteria associated with periodontopathic biofilms; one study evaluated periodontitis by clinical parameters and also assessed pro-inflammatory cytokines levels (IL-1, IL-6, and TNF-α) in serum." (PMID 34108875, 2021). "Surprisingly, salivary levels of TNF-α, IL-6, IL-8, and IL-17A can be affected not only by periodontitis but also in RA." (PMID 33672771, 2021). "Although an increased level of IL-6 was detected in the GCF of chronic periodontitis patients, the role of this cytokine in host defense at the oral mucosa site requires further investigation." (PMID 33562334, 2021). "In this way, when periodontitis becomes chronic, negative regulation of inflammation through the anti-inflammatory cytokines IL-4, IL-6, IL-10, IL-11, and IL-13 becomes predominant." (PMID 34707462, 2021). "In this study, PGFE inhibited the production of TNF-α, IL-1β, and IL-6, which are the major cytokines involved in periodontitis induced by PG-LPS, as well as the pro-inflammatory mediators NO and PGE2." (PMID 33287198, 2020).
periodontitis (continued). "Patients with severe periodontal disease had higher levels of TNF-α in the blood circulation, and the cytokines TNF-α, IL-6 and IL-1β are insulin antagonists, which play an important role in the pathogenesis of periodontitis." (PMID 32634783, 2020). "A previous meta-analysis aimed to compare levels of different cytokines in healthy and periodontitis subjects, with response to the treatment indicating increased IL-6 in GCF in the periodontitis group." (PMID 33081038, 2020). "IL-6 is a significant proinflammatory cytokine in DM and periodontitis pathogenesis, bone resorption, and osteoclast development." (PMID 33263670, 2020). "For that purpose, we measured the serum-levels of cardiac (proBNP, TpI) and inflammatory markers (CRP, IL-6) and compared these values between healthy individuals and periodontitis patients in pre-therapy samples." (PMID 32857064, 2020). "Peripheral neutrophils secrete excessive IL-1β, IL-8, IL-6, and tumor necrosis factor-α in patients with periodontitis." (PMID 32698486, 2020). "Using a meta-analytical approach, a previous study found that MMP-8, MMP-9, IL-1β, IL-6, and Hb were salivary biomarkers with good capability to detect periodontitis in systemically healthy subjects." (PMID 33383828, 2020). "Roles of inflammatory cytokines such as interleukin (IL)-1β and IL-6 in periodontitis have been explored by targeting fibroblasts, epithelial cells and macrophages." (PMID 31968635, 2020). "Interleukin 6 levels are higher in periodontitis patients when compared with those of control groups." (PMID 32267380, 2020). "Although it is well established that RA affects periodontitis clinically, and that especially the treatment of RA resulted in the improvement of periodontitis, IL-6 production in mouse gingival tissue of the LA group was similar to that of the Ctrl group." (PMID 33076980, 2020). "Several previous meta-analyses bring results on the possible association among polymorphisms in IL1A, IL1B, IL6, IL10 and IL17A/F genes and diverse clinical aspects of periodontitis, as well as dental implant failure." (PMID 32075624, 2020). "Interleukin-6 (IL-6) and interleukin-8 (IL-8) are the prominent pro-inflammatory cytokines that are closely related to periodontitis, which leads to connective tissue damage and alveolar bone loss." (PMID 32244806, 2020). "MMP production during the acute phase of periodontitis is elevated by IL-1 or IL-6 produced by neutrophils." (PMID 33294463, 2020). "IL6 is a multifunctional pro-inflammatory cytokine that is highly expressed in patients with periodontitis." (PMID 32867386, 2020). "Patients with severe periodontitis have increased systemic inflammation (elevated cytokines such as IL-6) compared with healthy controls, whereas treatment of periodontitis reduces inflammation load." (PMID 32714134, 2020). "In fact, TNF-α and IL-6 are correlated with the clinical indicators of periodontitis severity as demonstrated by previous studies." (PMID 32509226, 2020). "This systematic review aimed to investigate the influence of periodontitis on post-transplant IL-6 serum levels of solid organ transplanted patients as compared to healthy subjects." (PMID 32230707, 2020). "At the gingival tissues, a significant increase in the mRNA levels of Th17-related genes -such as IL-6, IL-17A, and Rorγt- were detected early at five days, and reaching its maximum at ten days post-periodontitis induction (≈ 10–20 fold-change)." (PMID 33149125, 2020). "An increase in serum IL-6 levels has also been reported for DM and periodontitis, which are both chronic diseases." (PMID 33263670, 2020). "Peripheral neutrophils from periodontitis patients release excess IL-1β, IL-8, IL-6 and tumour necrosis factor (TNF)-α when stimulated by periodontal pathogens." (PMID 32489774, 2020). "C-reactive protein and interleukin-6 are inflammatory derivatives produced in the presence of periodontitis and in the pathophysiology of coronary disease." (PMID 32215496, 2020).
periodontitis (continued). "The authors of another study have shown that P. gingivalis, in patients with chronic periodontitis, induces the production of IL-6, which was significantly increased in carriers of the IL-6 gene −174G allele." (PMID 33327639, 2020). "Several studies have found hypomethylation profiles within the interferon (IFN)-γ, IL-6, and TNF-α promoters, which was associated with increased IFN-γ, IL-6, and TNF-α transcription in gingival biopsies from patients with periodontitis." (PMID 33343358, 2020). "The periodontitis group exhibited an elevated level of IL-6 and a lower level of ARG-1 compared to the healthy group, while in the cell injection group, the IL-6 level was significantly suppressed." (PMID 33195441, 2020). "This study aimed to evaluate the effects of local application of vitamin C in tissue levels of AGE, IL-6, 8-OHdG, and MMP-8, in serum levels of CTX and periodontal attachment loss in diabetic rats with induced periodontitis." (PMID 33263670, 2020). "This systematic reviewed aimed to investigate the influence of periodontitis on post-transplant IL-6 serum levels transplant recipients and, therefore, if the patient is predisposed to a superior systemic inflammatory state." (PMID 32230707, 2020). "The results of qRT‐PCR revealed that the expression of inflammatory factors Tnfα and Il6 in the periodontal area was upregulated in the periodontitis (Pg + GFP), arthritis (CIA + GFP) and comorbidity (CIA + Pg + GFP) groups." (PMID 31737959, 2020). "Following, the influence of periodontitis on post-transplant IL-6 serum levels was sourced from three systematically selected case-control studies." (PMID 32230707, 2020). "Here, we showed an elevation of serum IL-6 in rats with periodontitis, which was more evident right after the induction process (24 h)." (PMID 31583485, 2020). "Experimental periodontitis posed an acute systemic inflammatory response with increased serum levels of IL-6 and PTX3 at 24 h post-induction, followed by a significant overexpression of sTWEAK at 7 days." (PMID 31583485, 2020). "The concentration of IL-6, IL-4 and IL-17 in the heart was assessed to examine the inflammatory response elicited by periodontitis." (PMID 32327711, 2020). "During the inflammatory process that takes place in periodontitis, a significant increasing of the expression of interleukins, such as IL-1β, IL-6 or transforming growth factor (TGF-1β), which plays a fundamental role, occurs." (PMID 31963913, 2020). "Accordingly, in our study, we evaluated the change in serum levels of pro-inflammatory and anti-inflammatory cytokines among periodontitis patients, and we found that they had higher significant levels of IL6, IL1b, and TNF compared to healthy individuals." (PMID 32604936, 2020). "There is evidence of elevated levels of serum interleukin (IL)-6 in periodontitis patients and lower levels of IL-4 and IL-18." (PMID 32489774, 2020). "Periodontitis as an inflammatory disease has been known to increase the levels of proinflammatory cytokines, including IL-1α, IL-1β, IL-6, and TNF-α." (PMID 33383828, 2020). "Further, increased serum levels of IL-6 contribute greatly to periodontal destruction and this higher prevalence is of concern for the progression of periodontitis." (PMID 32230707, 2020). "It has been reported that TLR4/MyD88 can activate the NF‐κB signaling pathway and induce the secretion of IL‐6, IL‐8, inducible nitric oxide synthase (iNos) and cyclooxygenase‐2, leading to periodontitis." (PMID 32687664, 2020). "To further confirm the correlation between chronic periodontitis and oral cancer, we also investigated the serum levels of interleukin-6 (IL-6), which is the most representative inflammatory marker." (PMID 31167516, 2019). "The expansion of the Th17 cells during periodontitis, on the other hand, is dependent on microbial dysbiosis and requires both IL-6 and IL-23 production." (PMID 31379856, 2019).
periodontitis (continued). "Leukocyte and macrophage number and protein level of tumor necrosis factor α (TNF-α) in periodontium and serum interleukin-6 level were downregulated by HF diet in periodontitis mice (P < 0.05)." (PMID 30719451, 2019). "Significant correlations between serum and GCF values were obtained in the periodontitis group for interleukin (IL) 1ra, IL‐6, and interferon γ at BL and for macrophage inflammatory protein 1β at M3 after treatment." (PMID 31049215, 2019). "Downregulated production of IL-6 is correlated with attenuation of inflammatory response in periodontitis." (PMID 31684930, 2019). "Persistently increased levels of various pro-inflammatory cytokines (e.g., TNF-α and IL-6) have been well documented in RA and periodontitis, and several cytokine-targeting therapies are successfully used in RA treatment." (PMID 31072030, 2019). "During periodontitis, stromal cells and immune cells express different cytokines and chemokines such as IL-4, IL6, IL-5, CXCL13, and APRIL that induce B cell migration and support their survival in the periodontium." (PMID 31379856, 2019). "As a crucial stimulator of alveolar bone resorption, IL-6 is overexpressed in the periodontium in periodontitis and greatly responsible for periodontal destruction." (PMID 31684930, 2019). "Periodontitis is a prevalent chronic inflammatory disease due to the host response (IL-1β, IL-6, TNF-α and IL-17A) to oral bacteria such as Porphyromonas gingivalis." (PMID 31848404, 2019). "It has been broadly reported to induce host cells like oral epithelial cells to produce a wide range of proinflammatory cytokines, including tumor necrosis factor-α (TNF-α), interleukin-6 (IL-6) and interleukin-8 (IL-8), promoting periodontitis progression." (PMID 31684930, 2019). "In particular, they produce pivotal pro-inflammatory cytokines in periodontitis such as IL-1β, IL-6 and TNF-α in response to bacterial challenge with the key periopathogen P. gingivalis through the NFκB and MAPK signaling pathways." (PMID 31848404, 2019). "Pivotal inflammatory cytokines in periodontitis, namely IL-1β, IL-6, TNF-α and IL-17A, mediate both periodontal inflammation and alveolar bone resorption." (PMID 31848404, 2019). "Correlations were significant in the periodontitis group for IL‐1ra, IL‐6, and IFN‐γ at BL and for MIP‐1β at M3." (PMID 31049215, 2019). "In our experiments, the IL-1β and IL-6 expression in gingival epithelia was elevated in all periodontitis mice compared with their normal controls." (PMID 31691738, 2019). "Interleukin-6 (IL-6) and interleukin-8 (IL-8) are prominent pro-inflammatory cytokines that are closely related to periodontitis, leading to periodontal tissue destruction and alveolar bone resorption." (PMID 30142971, 2018). "The IL-6 messenger RNA (mRNA) was highly expressed in the periodontal ligament cells during periodontitis." (PMID 29453398, 2018). "Recent studies also reported that the expression of IL-6 contributed to the progress of chronic periodontitis." (PMID 30140411, 2018). "They found that women with preterm delivery exhibited significantly more periodontitis and showed an increase in the levels of IL-6 and PGE2 in the crevicular fluid compared with the term delivery group." (PMID 30154640, 2018). "For example, vitamin D has been reported to be able to inhibit the activity of some cytokines related to periodontitis and dementia by decreasing IL-6, IL-8, and TNF-α expression." (PMID 30618721, 2018). "PgLPS is a crucial factor in the development of periodontitis, and has been reported to promote the production of IL-1, IL-6, and IL-8." (PMID 29401750, 2018). "Among the CD4+ T-cell subsets, TH17 cells exclusively accumulated in the oral mucosa and draining lymph nodes during oral infection, consistent with high expression of TH17-related cytokines Il17a and Il6 in the oral mucosa of periodontitis-induced mice." (PMID 29453398, 2018).